GSDMB (gasdermin B)
Diseases named in the same sentence as GSDMB in open-access papers (continued):
Sharing a sentence is not in itself a finding about the gene and the disease.
viral infections (5 papers, 2021 to 2025). "GSDMB is expressed in AECs and promotes pyroptosis, particularly during viral infections and IFN-γ stimulation." (PMID 40687950, 2025). "In Chinese populations, GWAS-detected loci in EXOC1 and GSDMB genes are suspected to influence immune response to viral infection." (PMID 33794208, 2021). "Furthermore, GSDMB promotes pyroptosis, a form of programmed cell death, contributing to airway epithelial damage, particularly during viral infections." (PMID 40687950, 2025). "In addition, GZMA from cytotoxic lymphocytes can cleave and activate GSDMB to induce pyroptosis in tumor cells as well as protect host cells during viral infection and prevent evasion from natural killer cell immunity." (PMID 37064151, 2023).
breast tumors (4 papers, 2016 to 2024). "Collectively, consistent results across different datasets demonstrate that high GSDMB expression identifies the most aggressive HER2+ breast tumours." (PMID 27462779, 2016). "Our study demonstrates that gasdermin B (GSDMB), mapped 175 kilo bases distal to ERBB2, is amplified and over-expressed in a subset (~60%) of HER2-positive breast tumours." (PMID 27462779, 2016). "Therefore, overexpression of GSDMB is a novel therapeutic target for HER2 breast malignancies, and intracellular delivery of GSDMB antibody utilizing nanoparticles greatly reduced the growth and metastatic development of HER2 breast tumors." (PMID 39247603, 2024). "Generally, GSDMB does not significantly affect breast tumor proliferation (as shown in this work and previous literature) but can mediate cancer survival upon therapy challenge." (PMID 36163066, 2022).
colorectal cancer (4 papers, 2022 to 2024). A primary or metastatic malignant neoplasm that affects the colon or rectum. "Specimens from 267 colorectal cancer cases were analyzed by immunohistochemistry to determine GSDMB expression, CD3+, CD4+, and CD8+ T lymphocytes, CD20+ B lymphocytes, CD68+ macrophages, and S100A8+ immune cells." (PMID 38711020, 2024). "The assays in vitro showed that high GSDMB expression enhanced the sensitivity of colorectal cancer cells to 5-fluorouracil." (PMID 38711020, 2024). "However, the correlations of the GSDMB expression in colorectal cancer with clinicopathological predictors, immune microenvironment, and prognosis are unclear." (PMID 38711020, 2024). "Colorectal cancer cells with high GSDMB expression are more sensitive to 5-fluorouracil." (PMID 38711020, 2024). "In colorectal cancer, GSDME might be a positive regulator in cell invasion and metastasis through cell migration and angiogenesis, while GSDMA, GSDMB and GSDMD might be a negatively regulator of cell migration." (PMID 35164740, 2022). "Though our analysis, we found that GSDMA, GSDMB, GSDMD and GSDME might be involved in colorectal cancer cell invasion and metastasis, and the former three might played as negative regulators while the last one played as a positive regulator." (PMID 35164740, 2022). "Interestingly, in colorectal cancer cell lines, we found the genes positively correlated with GSDMA had no intersection (none gene) with the genes negatively correlated with GSDMB, but it had intersection (1022 genes) with the genes positively correlated with GSDMB." (PMID 35164740, 2022).
cutaneous melanoma (4 papers, 2021 to 2023). A primary melanoma arising from atypical melanocytes in the skin. "GSDMB mutation was more likely associated with cutaneous melanoma." (PMID 35164740, 2022). "Intrahepatic cholangiocarcinoma, cutaneous melanoma, uterine endometrioid carcinoma and uterine mixed endometrial carcinoma had the highest GSDMA (6.67%), GSDMB (2.7%), GSDME (6.52%) and PJVK (4.76%) mutation frequency, respectively." (PMID 35164740, 2022). "GSDMB gene is an unfavorable prognostic marker in KIRC and PRAD and a favorable prognostic marker in bladder urothelial carcinoma (BLCA) and skin cutaneous melanoma (SKCM)." (PMID 37064151, 2023).
eczema (4 papers, 2019 to 2020). "GSDMB rs921650 was characterized as a strong risk factor for eczema." (PMID 32325630, 2020).
esophageal cancer (4 papers, 2015 to 2022). A primary or metastatic malignant neoplasm involving the esophagus. "In human cancer cell lines endogenously expressing GSDMB, specifically OE19 (esophageal carcinoma), SW837 (CRC), and SKCO1 (CRC), it was further shown that GzmA delivery through electroporation or perforin was sufficient to induce GSDMB-mediated pyroptosis." (PMID 34429144, 2021).
multiple sclerosis (4 papers, 2013 to 2026). A progressive autoimmune disorder affecting the central nervous system resulting in demyelination. "The determination of the potential role of changes in circRNA synthesis and GSDMB alternative splicing (AS) in the development of susceptibility to multiple sclerosis (MS) continues to pose challenges." (PMID 38001884, 2023). "Building on our identification of the significant knowledge gaps surrounding these molecules, future studies should specifically address: Could GSDMB variants, previously associated with multiple sclerosis (MS), also be implicated in MS‐related peripheral neuropathies?" (PMID 41574659, 2026). "Clinically, reduced GSDMB mRNA affects multiple sclerosis (MS) exacerbations; yet its expression and pathophysiological roles in PNS remain enigmatic." (PMID 41574659, 2026). "In support of a potential involvement of GSDMB in the development of multiple sclerosis (MS), it was demonstrated that reducing the expression of GSDMB in memory CD4+ T-cells resulted in an increased production of cytokines, including tumour necrosis factor (TNF), interleukin (IL)-13, and IL-16." (PMID 38001884, 2023).
autoimmune disorders (3 papers, 2017 to 2023). "Literature data suggest an involvement of GSDMB in inflammation and autoimmunity." (PMID 28272342, 2017).
Clear Cell Renal Cell Carcinoma (3 papers, 2021 to 2023). "Nonetheless, the correlation of GSDMB with immune infiltrates and its prognostic values in clear cell renal cell carcinoma (ccRCC) are still undefined." (PMID 34957313, 2021).
colitis (3 papers, 2022 to 2024). Inflammation of the colon. "Taken together, these data demonstrated that intestinal expression of GSDMB caused more severe colitis in vivo, at least partially by triggering pyroptosis." (PMID 38982510, 2024). "Since 4‐OI suppressed GSDMB‐dependent pyroptosis, we next evaluated the anti‐inflammatory effect of 4‐OI on experimental colitis in vivo." (PMID 38982510, 2024). "In our study, we found that 4‐OI significantly alleviated experimental colitis by inhibiting GSDMB‐mediated pyroptosis, at least in part." (PMID 38982510, 2024). "Correspondingly, western blot analysis of colonic tissues confirmed that 4‐OI was able to block proteolytic cleavage of GSDMB in Rosa26‐lsl/lsl‐GSDMB;Villin‐Cre colitis mice." (PMID 38982510, 2024). "Moreover, 4‐OI alleviates inflammation by suppressing GSDMB‐induced pyroptotic cell death during acute colitis models in intestinal epithelial GSDMB conditional transgenic mice." (PMID 38982510, 2024).
hepatocellular carcinoma (3 papers, 2014 to 2025). A malignant tumor that arises from hepatocytes. "Although GSDMB expression has been reported in the secretory cells in gastric and hepatic carcinomas, there are some discrepancies in its expression pattern depending on the tissue or cell system analyzed." (PMID 24675552, 2014).
lung adenocarcinoma (3 papers, 2022 to 2023). A carcinoma that arises from the lung and is characterized by the presence of malignant glandular epithelial cells. "Methylation analysis showed that promoter methylation negatively correlated with GSDMB expression level in KIRC (p < 0.001), uterine corpus endometrial carcinoma (UCEC) (p < 0.01), lung adenocarcinoma (LUAD) (p < 0.001), and pancreatic adenocarcinoma (PAAD) (p < 0.001)." (PMID 37064151, 2023).
prostate carcinoma (3 papers, 2022). A carcinoma that arises from epithelial cells of the prostate gland. "In addition, we used qRT-PCR to compare the expression of hub genes (CHMP4C, GSDMB, NOD2, PLCG1, CYCS, GPX4) between prostate cancer cell lines (LNCap, PC3, DU-145) and the normal prostate epithelial cell line (RWPE-1)." (PMID 36386841, 2022).
psoriasis (3 papers, 2022 to 2024). An autoimmune condition characterized by red, well-delineated plaques with silvery scales that are usually on the extensor surfaces and scalp. "Our idea is that, potentially, elevated levels of GSDMB indicate its stimulating effect on cell proliferation, whereas hyperproliferation of keratinocytes is a hallmark of psoriasis (Rendon and Schäkel, 2019)." (PMID 38693919, 2024). "GSDMB has been suggested to be involved in the proliferation and migration of cells and impaired keratinocytes proliferation and differentiation is a hallmark of psoriasis, moreover GSDMB has been implicated in the pathogenesis of several disorders associated with psoriasis." (PMID 38693919, 2024). "Elevated serum GSDMB and decreased urinary GSDMB/creatinine concentration ratio could be potential psoriasis markers, associated particularly with cell migration." (PMID 38693919, 2024). "Our results suggest that the downregulation of GSDMB may be involved in the abnormal keratinization of psoriasis, and provide insights for further study of the association between psoriasis and GSDMB." (PMID 36607980, 2023). "Our aim was to investigate the role of gasdermin B (GSDMB) in psoriasis, the second protein from the gasdermin family, involved in cell death and proliferation." (PMID 38693919, 2024). "GSDMB supposedly plays a different role in psoriasis than other gasdermins because its primary function seems to be not pyroptosis but regulation of cell migration." (PMID 38693919, 2024). "In the future, we would also like to study the influence of classic antipsoriatic agents and biological drugs on GSDMB in psoriasis." (PMID 38693919, 2024). "Our study adds to the current state of knowledge about psoriasis concerning the potential involvement of GSDMB." (PMID 38693919, 2024). "A more suitable explanation would be that GSDMB affects cell adhesion and controls cell proliferation, and considering we found it overexpressed in psoriasis, it is convergent with the increased proliferation rate of psoriatic epidermis." (PMID 38693919, 2024). "GSDMB serum concentration was significantly higher in patients with long-lasting psoriasis (p = 0.0278), however insignificantly compared to the group with shorter duration (p > 0.05)." (PMID 38693919, 2024). "Our results suggest that the down-regulated expression of GSDMB gene in psoriatic lesions is a suitable model for future studies of the relationship between psoriasis and GSDMB." (PMID 36607980, 2023). "Future studies can focus on the correlation between GSDMB and abnormal T cell function in psoriasis lesions." (PMID 36607980, 2023). "Our study revealed significantly more prominent expression of GSDMB in psoriatic plaques compared to uninvolved skin and controls, as well as higher serum GSDMB concentration which could indicate GSDMB role in psoriasis pathogenesis." (PMID 38693919, 2024). "In this study, we decided to investigate the role of GSDMB in psoriasis." (PMID 38693919, 2024). "Elevated serum GSDMB and decreased urinary GSDMB/creatinine concentration ratio could potentially be investigated as psoriasis biomarkers." (PMID 38693919, 2024). "As for another cytokine, that could provide a link between psoriasis and GSDMB, it has been demonstrated in vitro that overexpression of GSDMB in human bronchial epithelium upregulates some genes, including TGF-β1." (PMID 38693919, 2024). "Taking into account that the lack of GSDMB had been linked to decreased cell proliferation in the past, psoriasis is known for decreased apoptosis, and those authors observed downregulation of GSDMB, these results do not correspond to psoriasis pathogenesis." (PMID 38693919, 2024). "By comparing the differential expression of GSDMB in the skin tissues of normal people and psoriasis patients, this study suggested that GSDMB might be related to psoriasis." (PMID 36607980, 2023).
psoriasis (continued). "GSDMB may play a role in the pathogenesis of psoriasis by affecting the differentiation of keratinocytes and the function of T cells." (PMID 36607980, 2023). "The gene GSDMB may play a role in the pathogenesis of psoriasis by influencing keratinocyte differentiation and the function of T cells in skin lesions." (PMID 36607980, 2023). "Hence, there is another piece of evidence of the GSDMB engagement in epithelial cell turnover that could be a potential contribution to psoriasis pathology." (PMID 38693919, 2024). "Therefore, downregulation of GSDMB gene, which is involved in cell proliferation, is likely to play a role in the accelerated differentiation of keratinocytes in the granular layer and stratum corneum of psoriasis." (PMID 36607980, 2023). "Therefore, skin insufficiency of psoriasis patients may be closely related to the downregulation of GSDMB expression." (PMID 36607980, 2023). "In contrast, psoriasis skin-derived S.B cells expressed high levels of pyroptosis-related genes, such as CASP1, CAPS8, GSDMA, GSDMB, and GSDMD." (PMID 35962439, 2022). "Considering our findings, namely, overexpression in psoriatic plaque compared to healthy skin and increased serum concentration compared to subjects without psoriasis, it is clear that GSDMB might be involved in psoriasis pathogenesis." (PMID 38693919, 2024). "However, GSDMB is to some extent unique to the human genome, so the effects of GSDMB on psoriasis proliferation and differentiation have not been tested in animal models." (PMID 36607980, 2023).
airway hyperresponsiveness (2 papers, 2021 to 2023). "GSDMB was highly expressed in bronchial epithelial cells from asthmatic patients, and human GSDMB-expressing transgenic mice showed spontaneous increases in airway hyperresponsiveness, peribronchial smooth muscle, and collagen deposition." (PMID 33406603, 2021).
bladder urothelial carcinoma (2 papers, 2023 to 2024). "In addition, it has been shown that increased expression of GSDMB isoform-3 correlates with a favourable outcome in urothelial bladder cancer." (PMID 39766111, 2024).
deafness (2 papers, 2022). An inherited or acquired condition characterized by the complete loss of the ability to hear from one or both ears. "Six types of GSDMs paralogous genes, namely GSDMA, GSDMB, GSDMC, GSDMD, and GSDME [also termed deafness, autosomal dominant 53 (DFNA5)], and pejvakin [PJVK; also termed deafness, autosomal recessive 59 9DFNB59)], have been found in humans." (PMID 36003332, 2022). "So far, there are six categories of human gasdermins classified based on the difference in the conserved domain: gasdermin A (GSDMA), gasdermin B (GSDMB), gasdermin C (GSDMC), GSDMD, GSDME/DFNA5 (deafness, autosomal dominant 5)), and DFNB59/Pejvakin)." (PMID 36119049, 2022).
melanoma (2 papers, 2021 to 2023). A malignant, usually aggressive tumor composed of atypical, neoplastic melanocytes. "Our study provided evidence on GSDMB that it was relevant to better OS of melanoma and highly expressed in NK cells (cluster 2), followed by CD8+ T cells (cluster 1)." (PMID 37620327, 2023). "In combination, the findings suggested that GZMA, GSDMB, NLRP1, CHMP4A, and IL18 deficiency, at least in part, are responsible for melanoma." (PMID 37620327, 2023). "Our study provided evidence on GSDMB that it was relevant to better OS of melanoma and highly expressed in NK cells." (PMID 37620327, 2023). "GZMA and GSDMB could be regarded as significant indicators of immune therapeutic strategies of melanoma." (PMID 37620327, 2023). "Histologically, melanoma tissues had fewer positive cells percentage of pyroptosis-related genes (PRGs), GZMA, GSDMB, NLRP1, IL18, and CHMP4A in epidermal than in normal skin." (PMID 37620327, 2023). "Multiplex immunofluorescence staining results furtherer confirmed GZMA+ cells and GSDMB+ cells are secreted by CD8 + T cells and NK cells, suggesting ruduced tumor immune cells leading to lower pyroptosis capability on anti-melanoma properties." (PMID 37620327, 2023). "Melanoma specimens secreted a minimal presence of GZMA+ merged CD8+ T cells (0.11%) and GSDMB+ merged CD57+ cells (0.08%), compared to the control groups exhibiting proportions of 4.02% and 0.62%, respectively." (PMID 37620327, 2023). "Histologically, melanoma tissues had fewer positive cells percentage of PRGs, GZMA, GSDMB, NLRP1, IL18, and CHMP4A in epidermal than in normal skin." (PMID 37620327, 2023). "The initial findings from the enzyme-linked immunosorbent assay (ELISA) indicated a statistically significant downregulation of pyroptosis protein expression in melanoma patients when compared to the control group, especially NLRP1, GZMA, and GSDMB, followed by CHMP4A and IL18." (PMID 37620327, 2023). "Although the clinical evidence implied that melanoma skin tissue reduced GZMA, GSDMB, NLRP1, IL18, and CHMP4A expression in epidermal, however, the result obtained with bulk-sorted samples could not explain the main scientific questions on cell sources heterogeneity." (PMID 37620327, 2023).
neuroblastoma (2 papers, 2022 to 2024). Neuroblastoma (NB) is the most common solid, extracranial childhood tumor. "Contrary to the adult tumor, we found that higher GSDMB expression neuroblastoma manifested prolonged overall survival." (PMID 35664308, 2022). "We measured the mRNA levels of the gasdermin family genes (GSDMA, GSDMB, GSDMC, GSDMD and GSDME) in all five wild-type NB cell lines to understand the genes activated in neuroblastoma." (PMID 38893185, 2024).
Obesity (2 papers, 2018 to 2025). Accumulation of substantial excess body fat. "The genes glycerol‐3‐phosphate dehydrogenase 1 like (GPD1L), gasdermin B (GSDMB) and molybdenum cofactor synthesis 1 (MOCS1) were upregulated after LIWL, and expression was increased in SAT of individuals with or without obesity of the LATC and OA cohorts." (PMID 40229590, 2025).
pancreatic adenocarcinoma (2 papers, 2022 to 2023). "GSDMB mRNA levels differed significantly between the clinical stages of six types of cancer, namely BLCA, COAD, KIRC, LUAD, pancreatic adenocarcinoma (PAAD), and rectum adenocarcinoma (READ)." (PMID 36003332, 2022).
pancreatic cancer (2 papers, 2021 to 2024). "Given that GSDMB and GSDME are also highly expressed in pancreatic cancer." (PMID 39358349, 2024). "We identified GSDMB, GSDMD, and GSDME as the top three genes expressed in pancreatic cancer." (PMID 39358349, 2024).
shigellosis (2 papers, 2023). Shigellosis is a bacterial infection leading to dysentery and is caused by Shigella, which are small, ubiquitous Gram-negative bacteria belonging to the enterobacteria family. "In this sense, human GSDMB is activated to attack intracellular Shigella in infected enterocytes, but mice are naturally resistant to Shigellosis and thus, lack GSDMB gene." (PMID 36899106, 2023).
adult onset asthma (1 paper, 2011). "In this study, we aimed to evaluate the association of polymorphisms in ORMDL3, GSDMB, ZPBP2 and IKZF3 and adult-onset asthma in a Chinese Han population." (PMID 21985515, 2011).
breast invasive carcinoma (1 paper, 2022). "GSDMB expression was significantly lower in tumor specimens of breast invasive carcinoma (BRCA), colonic adenocarcinoma (COAD), and kidney chromophobe (KICH), compared to healthy tissues." (PMID 36003332, 2022).